PIN1 (peptidylprolyl cis/trans isomerase, NIMA-interacting 1)
Diseases named in the same sentence as PIN1 in open-access papers (continued):
Sharing a sentence is not in itself a finding about the gene and the disease.
atherosclerosis (5 papers, 2016 to 2022). A disease characterized by the build-up of fatty material and calcium deposition in the arterial wall resulting in partial or complete occlusion of the arterial lumen. "Taken together, our results implicate Pin1 in mechanisms underlying endothelial dysfunction and vascular inflammation in atherosclerosis." (PMID 28300760, 2017). "We and others have previously shown that the peptidyl-prolyl isomerase Pin1 acts as a critical driver of vascular cell proliferation, apoptosis and inflammation, and is implicated in several cardiovascular diseases such as atherosclerosis, coronary restenosis, and cardiac hypertrophy." (PMID 34379232, 2022). "Therefore, it is possible that variants in BRD4 and PIN1 genes may lead to decreased vascular elasticity by destroying endothelial cells and causing atherosclerosis." (PMID 33148187, 2020). "In summary, our findings demonstrate that Pin1 inhibition suppresses vascular inflammation and atherosclerosis as well as the activation of NF-κB signaling in ApoE−/− mice." (PMID 28300760, 2017). "Together, these results suggest that inhibition of Pin1 attenuates atherosclerosis by a lipid-independent manner." (PMID 28300760, 2017). "In summary, our findings confirmed the critical role of Pin1 in the early stage of vascular inflammation and atherosclerosis." (PMID 28300760, 2017). "Taken together, these results indicate that the NF-κB signal pathway is involved in Pin1-regulated vascular inflammation and atherosclerosis." (PMID 28300760, 2017). "Our findings indicate that Pin1 plays a vital role on the development of vascular inflammation and atherosclerosis." (PMID 28300760, 2017). "Pin1 has been found to act as a critical driver of vascular cell proliferation, apoptosis, and inflammation, with implication in many cardiovascular diseases (e.g., atherosclerosis, coronary restenosis, and cardiac hypertrophy)." (PMID 34943794, 2021). "Herein, we investigate whether Pin1 regulates vascular inflammation and atherosclerosis, and clarify its mechanisms in these processes." (PMID 28300760, 2017). "To clarify whether the ERK, JNK, and NF-κB signal pathways are involved in the Pin1-dependent regulation of vascular inflammation and atherosclerosis, we determined the activities of ERK, JNK, and NF-κB in the aortas." (PMID 28300760, 2017). "In the present study, we uncovered three important insights into roles for Pin1 in atherosclerosis." (PMID 28300760, 2017). "The data suggest that the NF-κB signaling pathway may be involved in Pin1-mediated vascular inflammation and atherosclerosis." (PMID 28300760, 2017). "Herein, we investigated whether Pin1 regulates vascular inflammation and atherosclerosis, and clarified its mechanism in these processes." (PMID 28300760, 2017). "Given the essential role of endothelial dysfunction in the initiation of atherosclerosis, Pin1 downregulation or inhibition may be a candidate for preventing atherosclerosis." (PMID 28300760, 2017). "Taken together, these findings indicate that Pin1 may play a critical role in the progression of vascular inflammation and atherosclerosis." (PMID 28300760, 2017). "Thus, the increases in adhesion molecules and inflammatory cytokines induced by Pin1 coordinate chronic inflammation in endothelial cells, possibly leading to atherosclerosis." (PMID 27618008, 2016). "Nonetheless, the pathophysiological role of Pin1 in atherosclerosis remains unknown." (PMID 28300760, 2017). "However, it is yet unknown which is involved in Pin1-regulated vascular inflammation and atherosclerosis in ApoE−/− mice." (PMID 28300760, 2017). "However, it is unknown whether Pin1 is involved in the development of atherosclerosis." (PMID 28300760, 2017). "Inhibiting Brd4 and Pin1 expression alleviates enhancer-mediated inflammatory transcription and atherosclerosis, which indicates that BRD4 and PIN1 play a vital role in the development of vascular inflammation and atherosclerosis." (PMID 33148187, 2020).
esophageal cancer (5 papers, 2013 to 2023). A primary or metastatic malignant neoplasm involving the esophagus. "The 6,7,4′-trihydroxyisoflavone reduced PIN1 PPIase activity, caused increased apoptosis of esophageal cancer, and inhibited proliferation." (PMID 36760500, 2023). "PIN1 is reported to be highly expressed in variety of human cancers, such as hepatic, prostate, lung, colorectal and esophageal cancers." (PMID 32258027, 2020). "Similarly, PIN1 is overexpressed in esophageal cancers and forms a prognostic marker and a novel therapeutic target for esophageal cancer." (PMID 34830970, 2021).
Hypertension (5 papers, 2012 to 2021). The presence of chronic increased pressure in the systemic arterial system. "Furthermore, Pin1 knock-out mice displayed an enhanced aortic phosphorylation of eNOS at Ser116, a reduction in NO production and in endothelium-dependent relaxation responses, thus suggesting that Pin1 deficiency-induced endothelial dysfunction and associated hypertension." (PMID 34943794, 2021). "Despite the discrepant results, it seems certain that Pin1 is involved in NO production in the aorta and we anticipate that elucidating of precise mechanism(s) will contribute to developing treatments for hypertension." (PMID 27618008, 2016).
osteoporosis (5 papers, 2016 to 2024). A condition of reduced bone mass, with decreased cortical thickness and a decrease in the number and size of the trabeculae of cancellous bone (but normal chemical composition), resulting in increased fracture incidence. "The direct binding to Pin1 is crucial for understanding the therapeutic implications of osteoporosis." (PMID 39062525, 2024). "Although changes in Pin1 expression and function with age remain unclear, either a stabilizer of Pin1 protein or a Pin1 activator may be of use for treating osteoporosis." (PMID 27618008, 2016). "Interestingly, Pin1 KO mice were reported to have features similar to those of osteoporosis." (PMID 27618008, 2016). "In a recent study, PIN1 was demonstrated in osteoporosis, mainly because the functional interaction between RUNX2 and PIN1 plays a key role in the skeletal system." (PMID 38099525, 2024).
cardiac hypertrophy (4 papers, 2016 to 2024). "Furthermore, Pin1 expressions are increased after TAC and Pin1 is involved in cardiac hypertrophy through regulating the Akt and Raf-MEK pathways." (PMID 27618008, 2016).
endothelial dysfunction (4 papers, 2017 to 2022). In vascular diseases, endothelial dysfunction is a systemic pathological state of the endothelium (the inner lining of blood vessels) and can be broadly defined as an imbalance between vasodilating and vasoconstricting substances produced by (or acting on) the endothelium. "In contrast, Pin1 knockout mice exhibited increased aortic endothelial nitric oxide synthase, endothelial dysfunction, and hypertension." (PMID 34379232, 2022). "In accordance with such evidence, pharmacological inhibition of Pin1 by juglone attenuated endothelial dysfunction, oxidative stress, as well as inflammatory processes, in streptozotocin-induced diabetic mice compared to vehicle-treated animals." (PMID 34943794, 2021). "Recent data revealed that Pin1-dependent conformational changes reduced nitric oxide availability and induced endothelial dysfunction." (PMID 28300760, 2017). "Meanwhile, evidence suggests that Pin1-dependent conformational changes reduce nitric oxide availability and induce endothelial dysfunction." (PMID 28300760, 2017). "It has been reported that Pin1 reduces nitric oxide availability and subsequently induces endothelial dysfunction." (PMID 28300760, 2017). "Prolyl-isomerase-1 (Pin1), as a unique peptidyl-prolyl isomerase, plays an important role in inflammation and endothelial dysfunction." (PMID 28300760, 2017). "Pin1 regulates endothelial nitric oxide synthase and induces endothelial dysfunction." (PMID 34379232, 2022). "Moreover, Pin1 inhibitor juglone prevents diabetes-induced endothelial dysfunction via NF-κB signalling." (PMID 34379232, 2022). "Interestingly, diabetic Pin1−/− mice were protected against mitochondrial oxidative stress, endothelial dysfunction, and vascular inflammation." (PMID 34943794, 2021). "Juglone as an inhibitor of Pin1 was evaluated in MCT-Shunt model of PAH, which demonstrates endothelial dysfunction, vascular remodelling, and neointimal formation similarly to human PAH." (PMID 34379232, 2022).
frontotemporal dementia (4 papers, 2009 to 2024). Frontotemporal dementia (FTD) comprises a group of neurodegenerative disorders, characterized by progressive changes in behavior, executive dysfunction and language impairment, as a result of degeneration of the medial prefrontal and frontoinsular cortices. "Such redirection of Pin1 has been also reported in brains of patients with frontotemporal dementias." (PMID 33083964, 2021). "In brains from autopsies, PIN1 was found to localize in the nucleus of normal neurons, but both in nuclei and cytoplasm in brains from patients suffering frontotemporal dementias (FTD) or AD." (PMID 30096758, 2018). "We performed analysis of coding and promoter regions of PIN1 in early- and late-onset AD and frontotemporal dementia (FTD) patients in comparison with healthy controls." (PMID 19909517, 2009). "Additionally, hypomethylation of the BIN1 gene at specific CpGs (26, 44, and 87) in the blood has been associated with an increased risk of LOAD, while hypermethylation of the PIN1 gene promoter distinguished frontotemporal dementia (FTD) from the hypomethylation observed in AD." (PMID 39678047, 2024).
Hepatic steatosis (4 papers, 2016 to 2024). Steatosis is a term used to denote lipid accumulation within hepatocytes. "We found that Pin1 deficiency can prevent the onset of MCDD-induced NASH featuring hepatic steatosis, inflammation and fibrosis." (PMID 27618008, 2016). "Importantly, Pin1 deficiency markedly suppressed the development of hepatic steatosis, inflammation and fibrosis observed in NASH mouse livers." (PMID 31795496, 2019). "In this study, we sought to identify a target for the treatment of NAFLD and showed that Pin1 is a key contributor to MCD-induced hepatic steatosis." (PMID 38892011, 2024). "The development of hepatic steatosis, inflammation, and fibrosis in NASH mice was dramatically prevented by Pin1 loss, which is significant since it indicates that Pin1 in the liver is necessary for the development of steatosis." (PMID 38892011, 2024). "Although the authors describe JNK activation by MLK3 as contributing to steatohepatitis progression, positive regulation of Pin1 by MLK3 may also be involved because Pin1 enhances the formation of hepatic steatosis as described in more detail below." (PMID 27618008, 2016). "Our study found that Pin1 can block ACC1 phosphorylation and enhance its activity by directly binding to ACC1, thus accelerating fatty acid synthesis and promoting hepatic steatosis by affecting the AMPK/ACC1 pathway, which may be an important mechanism by which Pin1 promotes the process of NAFLD." (PMID 38892011, 2024). "Hepatic Pin1 expressions are increased by either an HFD or MCDD, and hepatic steatosis does not occur in Pin1 knockout (KO) mice." (PMID 31795496, 2019).
ischemic stroke (4 papers, 2021 to 2024). A stroke disorder caused by obstruction of blood flow to the brain, due to thrombotic (local blood clot formation) or embolic (due to a blood clot or other material traveling from another site) event. "In line with this hypothesis, Pin1 has been reported to play a key role in acute neurological conditions associated with subsequent neurodegeneration, such as ischemic stroke, where it promotes neuronal death by acting on Notch1 signaling pathway." (PMID 33083964, 2021). "Pin1 also regulates the Notch pathway in ischemic stroke pathogenesis to promote neuronal death." (PMID 38727267, 2024). "While PIN1 could facilitate the stability of Notch1 intracellular domain (NICD1) and promote the proapoptotic function of NICD1 following ischemic stroke." (PMID 37305740, 2023).
liver fibrosis (4 papers, 2019 to 2024). "Pin1 upregulation in mouse and human fibrotic liver tissues, and Pin1-dependent epithelial-mesenchymal transformation activation pathways are potentially associated with liver fibrosis." (PMID 34128158, 2021). "In addition, the results of Picric Sirius Red (PSR) staining revealed that liver fibrosis was less severe in Pin1 deficiency." (PMID 38892011, 2024). "The effects of Pin1 on lipid accumulation, hepatic fibrosis, and oxidative stress were evaluated by biochemical analysis, glucose and insulin tolerance tests, histological analysis, IHC, RT-qPCR and Western blot assays." (PMID 38892011, 2024). "In clinical research, Pin1 has emerged as an independent predictor of liver fibrosis, with serum Pin1 levels being correlated with the histopathological stages of liver fibrosis in NASH." (PMID 38711994, 2024). "Furthermore, treatment with the Pin1 inhibitor juglone reportedly ameliorates drug-induced liver fibrosis." (PMID 31795496, 2019). "Pin1 has been found to be upregulated in NASH mouse models and promotes liver fibrosis through various pathways." (PMID 38711994, 2024). "This study also revealed that Pin1 promotes STAT3-mediated epithelial–mesenchymal transition, thereby inducing liver fibrosis." (PMID 31795496, 2019). "The serum Pin1 levels were found to correlate with histopathological features in patients with NASH and to be independent predictors of advanced liver fibrosis." (PMID 31795496, 2019). "Pin1 downregulation, either through its inhibitors or siRNA, reduces the expression of collagen 1a1/2, α-SMA, and fibronectin, indicating its pivotal role in ECM component production in hepatic stellate cells (HSCs) and liver fibrosis." (PMID 38711994, 2024). "Therefore, we consider the inhibition of increased Pin1 to be a promising approach to treating NASH and preventing hepatic fibrosis." (PMID 31795496, 2019).
lymphoma (4 papers, 2007 to 2018). A malignant (clonal) proliferation of B- lymphocytes or T- lymphocytes which involves the lymph nodes, bone marrow and/or extranodal sites. "Despite a basal leakiness of the shPin1 construct, causing a reduction in Pin1 levels relative to a control shRNA (shRen), administration of doxycycline further reduced Pin1 expression, reducing cell proliferation in vitro in two independent Eμ-myc lymphomas." (PMID 26943576, 2016). "Eμ-myc Pin1+/+ and Eμ-myc Pin1+/− mice developed lymphomas with similar latency (average onset: 108 days) and penetrance (86% and 92% respectively)." (PMID 26943576, 2016). "Pin1 silencing in lymphomas retarded disease progression in mice, making Pin1 an attractive therapeutic target in Myc-driven tumors." (PMID 26943576, 2016). "In Eμ-myc Pin1−/− lymphomas, instead, expression of these genes was back to the levels observed in the Pin1+/+ counterparts." (PMID 26943576, 2016). "Overall, these data indicate that Pin1 deletion affects the Notch3-dependent tumor progression and invasion properties of lymphoma cells in vivo." (PMID 26876201, 2016). "A similar effect occurred upon silencing of Pin1 in already established lymphomas." (PMID 26943576, 2016). "Finally, based on a reverse-genetics approach, we provide proof-of-principle experiments validating Pin1 as a therapeutic target in Myc-driven lymphoma." (PMID 26943576, 2016). "Finally, in line with our data in Pin1−/− mice, knockdown of Pin1 in Eμ-myc lymphomas impaired their proliferations in vitro and significantly enhanced survival of disease-bearing mice." (PMID 26943576, 2016). "We next asked whether Pin1 would be required for the growth of established lymphomas." (PMID 26943576, 2016).
oral squamous cell carcinoma (4 papers, 2018 to 2024). "A study conducted in Eastern China found that the risk of oral squamous cell carcinoma was significantly increased in 209 patients with PIN1 polymorphism." (PMID 39202474, 2024). "PIN1 reduces the ΔNp63 ubiquitination induced by WWP1 to enhance the proliferation of oral squamous cell carcinoma." (PMID 39202474, 2024). "Similarly, cadmium (Cd)-induced autophagy was regulated by PIN1 in oral squamous cell carcinoma (OSCC) cell line." (PMID 36340199, 2022).
renal fibrosis (4 papers, 2016 to 2025). A final common manifestation of a wide variety of chronic kidney diseases characterized by glomerulosclerosis and tubulointerstitial fibrosis. "As a phosphorylating enzyme, future studies should investigate Pin1 upregulation in renal fibrosis and its association with a high phosphorus diet." (PMID 40643473, 2025). "In this study, we have identified Pin1 as a critical regulator of renal fibrosis, calcium deposition, tubular injury and inflammation after HPD." (PMID 26914452, 2016). "Our results suggest that diet containing high Pi induces rapid renal fibrosis before a significant impact on renal function and that Pin1 plays an important role in the fibrotic process." (PMID 26914452, 2016). "Here, we show that the peptidyl-prolyl isomerase Pin1 is an important molecular contributor that facilitates renal fibrosis in a well-characterized animal model." (PMID 26914452, 2016). "Notably, the renal fibrosis induced by the high-phosphate diet was attenuated by knocking out expression of the fibrotic facilitator peptidyl-prolyl isomerase, (Pin1)." (PMID 40643473, 2025). "We present existing evidence for the involvement of Pin1 in conditions such as AKI, CKD-SHPT, DN, renal fibrosis, and RCC." (PMID 38711994, 2024). "Our results suggest that Pin1 blockade can attenuate the pro-fibrogenic milieu and reduce ECM deposition during pathological renal fibrosis." (PMID 26914452, 2016). "In aggregate, these results suggest that Pin1 regulates HPD-induced renal fibrosis through non-Smad pathways and possibly through modulation of plasma Ca." (PMID 26914452, 2016). "Therefore, Pin1 plays a crucial role in maintaining ECM balance and preventing renal fibrosis." (PMID 38711994, 2024).
allergic asthma (3 papers, 2013 to 2021). A asthma with a basis in a pathological type I hypersensitivity reaction. "Here we show that interleukin receptor associated kinase M (IRAK-M) is a PIN1 target critical for IL-33 signaling in allergic asthma." (PMID 29686383, 2018). "Pin1 was required for Eos differentiation and maturation in the bone marrow, as well as peripheral blood Eos survival and transmigration in allergic asthma." (PMID 33494375, 2021). "We demonstrated that PIN1 isomerization modulates the pro-apoptotic activity of BAX and the mRNA binding ability of AUF1 thereby influencing immune cell death and cytokine production associated with allergic asthma." (PMID 23675491, 2013).